CD37 (CD37 molecule)
Description:
Structural component of specialized membrane microdomains known as tetraspanin-enriched microdomains (TERMs), which act as platforms for receptor clustering and signaling. Participates thereby in diverse biological functions such as cell signal transduction, adhesion, migration and protein trafficking. Upon ligand binding, two signaling pathways are activated, one acting through phosphorylation by LYN leading to cell death or a survival pathway with activation of GSK3B. Plays an essential role essential for clustering of integrin ITGA4/ITGB1 and promotes its mobility in the plasma membrane of B-cells. In turn, participates in ITGA4/ITGB1 integrin-mediated antiapoptotic signaling through AKT (By similarity). Also plays a role in the migration of dendritic cells and neutrophils to draining lymph nodes, as well as in their integrin-mediated adhesion (By similarity). Negatively regulates IL-6 responses through direct interaction with SOCS3 thereby preventing constitutive IL-6 signaling. Alternatively, inhibition of IL-6 signaling can also occur via interaction and stabilization of DECTIN1/CLEC7A at the cell membrane to inhibit its ability to promote the production of IL-6.
Synonyms: TSPAN26; GP52-40
Tractability: Antibody: a drug acting on it is in phase 2 or 3 trials; UniProt places it where antibodies can reach, with high confidence; UniProt predicts a signal peptide or a membrane-spanning region; its Gene Ontology location is reachable by antibodies, with medium confidence; the Human Protein Atlas places it where antibodies can reach. PROTAC: ubiquitination databases record sites on it; its protein half-life has been measured. Other modalities: a drug acting on it is in phase 2 or 3 trials.
Target class: Membrane receptor
Gene: Protein-coding gene on chromosome 19 (49,335,171 to 49,343,335, forward strand). Ensembl gene ENSG00000104894.
Subcellular location: Cell membrane
Subcellular location (Human Protein Atlas): Golgi apparatus; Plasma membrane
Gene Ontology:
Molecular function: protein binding
Cellular component: extracellular exosome; immunological synapse; membrane; plasma membrane
Genetic constraint (gnomAD): Loss-of-function variants: 37 observed, 40.05 expected, observed/expected ratio (o/e) 0.92, 90% interval 0.71 to 1.22. The upper end of that interval is the gene's LOEUF score, 1.22, which puts it in group 5 of 6, group 1 being the genes least tolerant of losing a copy. Missense variants: 351 observed, 378.84 expected, observed/expected ratio (o/e) 0.93, 90% interval 0.85 to 1.01. Synonymous variants: 146 observed, 158.95 expected, observed/expected ratio (o/e) 0.92, 90% interval 0.8 to 1.05.
Homologues: Orthologues: chimpanzee CD37 (96% identical), macaque CD37 (95% identical), mouse Cd37 (80% identical), guinea pig CD37 (79% identical), dog CD37 (75% identical), pig CD37 (74% identical), rat Cd37 (73% identical), tropical clawed frog cd37 (41% identical), zebrafish cd37 (31% identical). Paralogues in human: CD82 (36% identical), TSPAN4 (25% identical), TSPAN10 (25% identical), CD151 (25% identical), CD53 (23% identical), TSPAN11 (23% identical), TSPAN19 (23% identical), TSPAN17 (22% identical), TSPAN1 (22% identical), TSPAN18 (22% identical), TSPAN8 (22% identical), TSPAN5 (22% identical), and 20 more.
Diseases named in the same sentence as CD37 in open-access papers:
CD37 is named in the same sentence as 71 diseases in open-access papers, as found by Europe PMC text mining. Sharing a sentence is not in itself a finding about the gene and the disease. The quoted sentences say what the papers report.
B-cell lymphoma (24 papers, 2014 to 2025). "In summary, these findings demonstrate that patients with CD37-deficient B-cell lymphoma accumulate lipids for storage within tumour tissues." (PMID 36100608, 2022). "Tetraspanin CD37 deficiency has been reported as a prognostic marker for aggressive B-cell lymphoma." (PMID 36100608, 2022). "To study the metabolic phenotype of these aggressive B-cell lymphomas, we generated CD37-deficient human DLBCL cell lines (BJAB, OciLy1) using CRISPR/Cas9 technology and used a CD37-deficient mouse model." (PMID 36100608, 2022). "Here, the authors show that CD37 interacts with the fatty acid transporter 1 to inhibit palmitate uptake and its deficiency leads to increased fatty acid metabolism which promotes tumorigenesis in B-cell lymphoma." (PMID 36100608, 2022). "Furthermore, CD37-deficiency leads to spontaneous development of aggressive B-cell lymphoma in mice." (PMID 36100608, 2022). "Importantly, blocking FA metabolism of CD37-deficient B-cell lymphomas diminished proliferation and viability, potentiating therapeutical exploitation." (PMID 36100608, 2022). "The crucial role of CD37 in B cell lymphoma formation comes from a murine model, where CD37-deficient mice spontaneously developed germinal center–derived B cell lymphoma in lymph nodes and spleens with a higher incidence than Bcl2 transgenic mice (50% vs. 20%)." (PMID 33333768, 2020). "Finally, we investigated whether the enhanced storage capacity of CD37-deficient lymphoma cells was also observed in primary human B-cell lymphoma tissues." (PMID 36100608, 2022). "AML cell lines displayed generally lower levels of CD37 than B cell lymphomas and required staining with a specific antibody, elucidating the previous conflicting reports on CD37 positivity." (PMID 38754420, 2024). "The immense importance of this study lies in discovering CD37 as a gatekeeper of the metabolic switch to FAO in aggressive B-cell lymphoma." (PMID 39518937, 2024). "CD37-targeting RIT has also been developed because CD37 is detected on not only mature normal B-cells but also the majority of B-cell NHL." (PMID 38464386, 2024). "CD37 is a tetraspanin protein expressed in various B cell lymphomas, including MCL, and has been found to mediate tumor survival signaling." (PMID 37626420, 2023). "In B-cell lymphomas, of which MALT lymphoma is an example, CD37 loss is known to be associated with decreased patient survival." (PMID 37206375, 2023). "CD37, whose expression correlates with favorable prognosis, can protect against the development of B cell lymphoma by interacting with the suppressor of cytokine signaling 3 (SOCS3) to inhibit IL-6 signaling." (PMID 36941633, 2023). "GEN3009 is a CD37-targeting biparatopic antibody in a phase-1 clinical trial for multiple B cell lymphomas, including R/R MCL (NCT04358458)." (PMID 37626420, 2023). "CD37 CAR T cells have been preclinically tested for efficacy in B cell lymphomas which exhibited robust effector functions, Th1-type cytokines expression, and tumor clearance in the MCL-PDX model." (PMID 37626420, 2023). "Most recently, CD37 has been demonstrated to inhibit fatty acid metabolism in aggressive B-cell lymphoma through interacting with fatty acid transporter protein 1 (FATP1) in the plasma membrane, and inhibiting the uptake and processing of exogenous palmitate." (PMID 36941633, 2023). "[89Zr]Zr-N-sucDf-NNV003 tumor uptake was evaluated by PET imaging of mice bearing human CD37-expressing REC1 B cell NHL or RAMOS Burkitt’s lymphoma xenograft tumors followed by ex vivo analysis." (PMID 35428777, 2022). "CD37 is a highly glycosylated transmembrane protein selectively expressed by normal B cells and the majority of B cell lymphomas and is specifically of interest for RIT, since CD37 receptor-antibody complexes are highly internalized in tumor cells." (PMID 35428777, 2022). "Here, we report tetraspanin CD37 as an essential and conserved inhibitor of fatty acid metabolism in aggressive B-cell lymphoma." (PMID 36100608, 2022).
B-cell lymphoma (continued). "Here, we identify tetraspanin CD37, a prognostic marker for aggressive B-cell lymphoma, as essential membrane-localized inhibitor of FA metabolism." (PMID 36100608, 2022). "Collectively, our results identify CD37 as a direct gatekeeper of the FA metabolic switch in aggressive B-cell lymphoma." (PMID 36100608, 2022). "Our work identified tetraspanin CD37 as an essential membrane-bound gatekeeper for a fatty acid metabolic switch in aggressive B-cell lymphoma via inhibitory interaction with FATP1." (PMID 36100608, 2022). "[89Zr]Zr-N-sucDf-NNV003 whole-body distribution and tumor-targeting were evaluated in BALB/c nude mice bearing CD37-expressing human REC1 B cell NHL xenograft tumors." (PMID 35428777, 2022). "Collectively, these results support a universal role for CD37 in the direct inhibition of LCFA uptake in B-cell lymphoma." (PMID 36100608, 2022). "Taken together, our study contributes key insights to the fast-growing, yet understudied, field of cancer metabolism and identifies CD37 as a gatekeeper of a fatty acid metabolic switch in aggressive B-cell lymphoma." (PMID 36100608, 2022). "Irrespective of the type of molecular interaction, our data demonstrate that CD37 is a key modulator of fatty acid metabolism via FATP1 inhibition in B-cell lymphoma." (PMID 36100608, 2022). "Early clinical studies of anti-CD37 agents have demonstrated that it is a viable therapeutic target in B cell NHL." (PMID 33523334, 2021). "CD37 is expressed on multiple tumor subtypes, including B cell NHL, CLL, Waldenstrom’s macroglobulinemia, T-ALL, PTCL (reported 82 % positive for CD37), and AML." (PMID 34332618, 2021). "CD19 and CD37 proteins are highly expressed in B-cell lymphoma and have been successfully targeted with different monotherapies, including chimeric antigen receptor (CAR)-T cell therapy." (PMID 33652767, 2021). "A number of anti-CD37 therapies are currently being investigated for the treatment of B-cell NHL, including radioimmunotherapy." (PMID 33523334, 2021). "The capacity of DuoHexaBody-CD37 to induce CDC in malignant B cells was further confirmed in CDC assays in vitro using 16 tumor cell lines with varying CD37 expression levels, derived from different B-cell lymphoma subtypes." (PMID 32341336, 2020). "In cancer, CD37 is highly expressed on malignant B cells in a variety of B-cell lymphomas and leukemias, including NHL and CLL14,15." (PMID 32341336, 2020). "Preclinical data from multiple B cell lymphoma cell lines have demonstrated a synergistic cytotoxic effect of an anti-CD37 naratuximab emtansine combined with anti-CD20 mAbs (rituximab, ofatumumab, and obinutuzumab)." (PMID 33333768, 2020). "This study defined an MTD and demonstrated preliminary activity of BI 836826 in patients with B cell NHL, thus further validating CD37 as a therapeutic target in this setting." (PMID 32172489, 2020). "DuoHexaBody-CD37 induces not only effective CDC against B cell lymphoma cell lines and primary CLL samples but also can induce efficient ADCC and antibody-dependent cellular phagocytosis (ADCP) in vitro by engaging FcγRs." (PMID 33333768, 2020). "Although BI 856826 will not undergo further clinical development, these results confirm CD37 as a valid therapeutic target in B cell NHL." (PMID 32172489, 2020). "In this study, CAR-T cells targeted against CD37 were proven both specific and efficient against B cell lymphoma in in vitro studies and in two xenograft lymphoma models in mice." (PMID 33333768, 2020). "Promising findings of CD37 as a novel therapeutic target for CARs in the treatment of B cell lymphoma have also been provided." (PMID 33333768, 2020). "Due to its restricted specificity for differentiated cells of the B-cell lineage, CD37 was considered to be a potential target for the treatment for B-cell lymphoma using an anti-CD37 antibody radiolabeled with iodine-131 (β−; T1/2 = 8.02 d; 606 keV)." (PMID 30769765, 2019).
B-cell lymphoma (continued). "The relevance of CD37 in tumor suppression has been recently shown in CD37−/− mice that spontaneously develop B-cell lymphoma, and in patients with CD37-negative B-cell lymphoma that have poor survival." (PMID 29896201, 2018). "An 131I conjugated mouse CD37 mAb was shown to induce complete remission in 6/6 patients with B cell lymphoma." (PMID 25285080, 2014). "In addition, CD37 represents a new promising target in aggressive B-cell lymphoma; see about CD37-directed naratuximab emtansine later in the text." (PMID 39518937, 2024). "In fact, CD37 has been recently described as a negative regulator of tumorigenesis in B cell NHL." (PMID 33333768, 2020). "Although the sponsor has decided not to pursue further clinical development of BI 836826, primarily due to changes in strategy reflecting recent changes in the treatment landscape for CLL, the results of this study support further clinical investigation of CD37 as a therapeutic target in B cell NHL." (PMID 32172489, 2020). "As CD37 has been demonstrated as a negative regulator of tumorigenesis in B cell lymphoma, it is important to investigate if anti-CD37 immunotherapy does not lead to the selection of CD37-deficient clones with increased proliferation/metastasis potential." (PMID 33333768, 2020). "Other promising B-cell markers in the therapeutic context are CD79B, expressed in more than 90% of B-cell lymphomas, CD30, CD37, and CD70." (PMID 39518937, 2024). "Our group and others have recently developed a CD37-targeting CAR T cell-based therapy mirroring the CD19CAR T cell approach described for the treatment of B cell leukemia, B cell lymphoma, and T cell lymphoma." (PMID 38754420, 2024). "CD37 also is highly expressed in B cell lymphomas, including CLL, and anti-CD37 CAR-T showed activity in mouse models, including against CD19 negative targets." (PMID 36980726, 2023). "We also characterized promising, clinically explored targets that are tested in blood cancers derived from B cells at various stages of development and maturation, including BAFF-R (B-ALL), CD37 (CLL, B cell lymphoma), and GPRC5D (MM)." (PMID 35681499, 2022). "Together, these results demonstrate a specific interaction between tetraspanin CD37 and the LCFA-transporter FATP1 on the cell surface of aggressive B-cell lymphoma." (PMID 36100608, 2022). "[177Lu]Lu-DOTA-NNV003, a radioimmunoconjugate targeting CD37, is developed as novel radioimmunotherapy (RIT) treatment for patients with B cell non-Hodgkin’s lymphoma (NHL)." (PMID 35428777, 2022). "The anti-tumor activity of DuoHexaBody-CD37 in vivo was evaluated in CDX models obtained by intravenous or subcutaneous injection of B-cell lymphoma-derived Daudi-Luc and DOHH-2 cells and CLL-derived JVM-3 cells, that express moderate to high levels of CD37." (PMID 32341336, 2020). "Clinical studies with the anti-CD37 agents otlertuzumab (TRU-016), IMGN529, and AGS67E suggest that targeting CD37 is a viable therapeutic strategy, with evidence of anti-tumor activity seen in patients with DLBCL, FL and other B cell NHLs." (PMID 32172489, 2020). "CD37 is significantly downregulated in aggressive B-cell lymphoma cell lines resistant to rituximab; nevertheless, this reduction in CD37 expression does not diminish the therapeutic efficacy of CD37-targeted CAR T-cell therapy." (PMID 40565133, 2025). "Separately, a knockout study of Cd37 in B-cell lymphoma in mice does not show IgM expression, consistent with our model ΔECD37, IGHM =−8.2." (PMID 37206375, 2023). "A preclinical study confirmed the high expression of CD37 on tumor cells of DLBCL, FL, MCL, MZL and CLL, which demonstrated the remarkable efficacy of anti-CD37 CAR-T to both CD19 positive B-cell lymphoma cell line and CD19 negative cell line in vitro." (PMID 34256851, 2021).
lymphoma (17 papers, 2015 to 2025). A malignant (clonal) proliferation of B- lymphocytes or T- lymphocytes which involves the lymph nodes, bone marrow and/or extranodal sites. "CD37 is already targeted in antitumor immunotherapy and its absence from lymphomas is associated with a poor prognosis." (PMID 40028321, 2025). "Several knockouts illustrate their biological functions such as infertility (CD9/CD81), lymphoma development (CD37), immunological deficiency (CD81), or renal insufficiency (CD151)." (PMID 37835445, 2023). "We now show that loss of CD37 reprograms lymphoma cells into high-energy producing, pro-survival/pro-proliferating aggressive tumours." (PMID 36100608, 2022). "We first established the uptake potential of palmitate in human lymphoma cells, since palmitate was specifically deprived from serum and was actively processed in B cells of CD37-deficient mice and human lymphoma cells." (PMID 36100608, 2022). "Next, we investigated the molecular mechanism underlying CD37-dependent inhibition of uptake and processing of exogenous palmitate in aggressive lymphoma." (PMID 36100608, 2022). "Among other mechanisms, the knockout of CD37 leads to the occurrence of lymphomas that appear to be linked to the constitutive activation of the IL6 signaling pathway." (PMID 30769765, 2019). "In this preprint, it is hypothesized that the presence of CD20 stabilizes CD37 in the cell membrane as increased internalization of anti-CD37 is measured on deficient CD20 lymphoma B-cell lines." (PMID 38983848, 2024). "However, the situation is more complex, as only CD37-deficient lymphomas can use palmitate because the membrane protein tetraspanin, CD37, inhibits a FA transporter by directly binding to it." (PMID 39518937, 2024). "Moreover, inhibition of carnitine palmitoyl transferase 1 A significantly compromises viability and proliferation of CD37-deficient lymphomas." (PMID 36100608, 2022). "Furthermore, the superior influx of acetyl-CoA via FAO allows excessive TCA intermediates to be used for alternative, more anabolic processes in CD37-deficient lymphoma." (PMID 36100608, 2022). "Furthermore, increased accumulation of TCA cycle-intermediates such as citrate, succinate and malate in CD37-deficient lymphoma cells indicated that palmitate was degraded via FAO to fuel the TCA cycle via acetyl-CoA." (PMID 36100608, 2022). "Both lipid droplet formation and TCA maintenance are drastically enhanced in CD37-deficient lymphoma and premalignant B cells, which may be of particular benefit within the germinal centre environment." (PMID 36100608, 2022). "Anti-CD81 mAbs are not yet in the clinic but there are anti-tetraspanin mAbs in early clinical development, such as the anti-CD37 BI 836826 currently developed in leukemia and lymphoma." (PMID 37046846, 2023). "Deletion of CD37 on lymphoma cells results in increased FA oxidation shown by functional assays and metabolomics." (PMID 36100608, 2022). "Taken together, these data indicate that palmitate is systemically depleted in mice with lymphoma in a CD37-dependent manner." (PMID 36100608, 2022). "To verify that this distinctive uptake profile was a direct consequence of CD37 expression, we performed rescue experiments in which full-length CD37 was re-introduced in CD37KO lymphoma cells." (PMID 36100608, 2022). "Together, these results show that CD37-deficiency in mice leads to increased uptake and processing of palmitate by CD37KO B cells, confirming the earlier observed phenotype in human lymphoma B cells." (PMID 36100608, 2022). "CD37 re-expression in CD37KO lymphoma cells resulted in a significant reduction in uptake of palmitate compared to mock-transfected cells, resembling the WT phenotype." (PMID 36100608, 2022). "The goal of this study was to target lymphoma with novel CD37, humanized CD37, and bi-specific humanized CD37-CD19 CAR-T cells." (PMID 33652767, 2021).